PTH (parathyroid hormone)
Diseases named in the same sentence as PTH in open-access papers (continued):
Sharing a sentence is not in itself a finding about the gene and the disease.
dementia (17 papers, 2009 to 2025). Loss of intellectual abilities interfering with an individual's social and occupational functions. "Our analysis is the first systematic review to examine associations between PTH, cognition and dementia, covering the whole spectrum of parathyroid conditions and also serum PTH levels." (PMID 26010883, 2015). "One cross-sectional and four case-control studies also provide some support for an association between serum PTH and poor cognitive function/impairment or dementia." (PMID 26010883, 2015). "In summary, mixed findings for both cognitive function and dementia were suggestive of an association with higher PTH levels though equivocal." (PMID 26010883, 2015). "We conducted a systematic review through January 2014 to evaluate the association between PTH and parathyroid conditions, cognitive function and dementia." (PMID 26010883, 2015). "Participants with elevated PTH levels (≥62ng/L; normal <55 ng/L) had a two-fold increased risk of cognitive decline and all-cause dementia over one and five years." (PMID 26010883, 2015). "Only one long-term prospective study was identified supporting a link between higher PTH levels and increased risk of dementia." (PMID 26010883, 2015). "Numerous studies have reported that age-induced increased parathyroid hormone plasma levels are associated with cognitive decline and dementia." (PMID 19825157, 2009). "Given the plausible mechanisms to suggest abnormal parathyroid hormone levels may lead to cognitive dysfunction and an increased risk of dementia, our study is an important contribution for disentangling this relationship." (PMID 39974053, 2025). "In addition, recent clinical studies have shown that elevated PTH levels are associated with an increased risk of cognitive decline and incident dementia in a general older population, independently of calcium and renal function." (PMID 34959925, 2021). "Elevated serum PTH (S-PTH) concentrations have been linked to poor cognition, vascular dementia, and all-cause dementia in some studies, but whether S-PTH concentrations affect the risk of AD specifically is unclear." (PMID 30200567, 2018). "Given the plausible mechanisms to suggest abnormal PTH levels may lead to cognitive dysfunction and an increased risk of dementia, further investigation is warranted." (PMID 26010883, 2015). "Calcium was hypothesized to be a potential confounder in one study and a potential mechanism to explain the association between PTH and cognitive dysfunction or dementia in sixteen studies." (PMID 26010883, 2015). "Therefore, our aim was to conduct a systematic review to update and evaluate the current research for the association of PTH and parathyroid conditions with cognitive function and dementia." (PMID 26010883, 2015). "No large, well-designed trial has investigated whether normalizing PTH levels is effective at improving cognitive outcomes or reducing the risk of dementia." (PMID 26010883, 2015). "PTH has been considered a candidate risk factor for senile dementia because sustained high levels of PTH in the brain may cause degeneration of specific brain regions due to Ca(2+) overloading." (PMID 19825157, 2009). "Moreover, recent findings suggest that elevated PTH levels may be associated with increased risk of cognitive decline and incident dementia." (PMID 26010883, 2015). "PTH affects cognitive activities, which include a variety of dementia-related symptoms, and it can penetrate the blood–brain barrier through PTH receptors found throughout the brain." (PMID 39224568, 2024). "Secondary hyperparathyroidism (SHPT), characterized by severely elevated parathyroid hormone levels (PTH), is a common metabolic abnormality and a potentially modifiable dementia risk factor in ESRD patients." (PMID 39407758, 2024). "Several mechanisms have been proposed to explain possible links between PTH, cognitive decline and dementia." (PMID 26010883, 2015).
dementia (continued). "Currently, this study along with the surgical intervention studies by Roman and colleagues concentrate the evidence to support a potentially independent role of PTH in cognition and dementia." (PMID 26010883, 2015). "Mixed evidence offers weak support for a link between PTH, cognition and dementia due to the paucity of high quality research in this area." (PMID 26010883, 2015). "Given the low to moderate quality and generally inadequate reporting, it is not possible to draw firm conclusions about the relationship between PTH and cognitive function or dementia." (PMID 26010883, 2015). "In general the reporting of these important covariates when they were included was inadequate, and their potential role in relation to PTH, cognition and dementia remains largely unclear." (PMID 26010883, 2015). "Findings from observational studies were generally mixed, and offer weak support for a link between PTH and cognitive function or dementia." (PMID 26010883, 2015). "Findings from six observational studies were mixed but suggest a link between higher serum PTH levels and increased odds of poor cognition or dementia." (PMID 26010883, 2015). "This systematic review synthesized 27 low and moderate quality studies of PTH and parathyroid conditions in relation to cognitive function or dementia." (PMID 26010883, 2015). "Key characteristics of studies relating to PTH levels, parathyroid conditions, cognitive function and dementia." (PMID 26010883, 2015). "Parathyroid hormone (PTH) is of interest in relation to cognitive function and dementia as it crosses the blood brain barrier and PTH receptors are found throughout the human brain." (PMID 26010883, 2015). "Conversely, two additional case-control studies reported significantly higher serum PTH in women with dementia compared to controls." (PMID 26010883, 2015). "Further studies are warranted to confirm the value of increased PTH levels coupled with increased P300 latency as putative biological markers of both dementia and OP." (PMID 19825157, 2009). "Abnormal parathyroid hormone levels play a role in neuronal calcium dysregulation, hypoperfusion and disrupted neuronal signaling and there is some support for a link between parathyroid hormone levels, cognition and dementia." (PMID 39974053, 2025). "Interestingly, several studies of patients with increased levels of PTH after parathyroidectomy normalized PTH have indicated marked improvement in cognitive function and signs of dementia." (PMID 34959925, 2021). "We can speculate whether this inability to increase PTH levels in response to a peripheral resistance is related to the severity of disease and especially to the inexorable evolution to dementia and akinetic mutism." (PMID 27415614, 2016). "In conclusion, there is currently no basis to suggest a causal relationship between PTH and cognitive function or dementia." (PMID 26010883, 2015). "To date, no trial has examined this relationship where PTH levels were successfully normalized in a large population at risk of dementia." (PMID 26010883, 2015). "Elevated PTH concentrations in dementia patients have been documented as well." (PMID 26010883, 2015). "Six studies examined the relationship between serum PTH levels and cognitive function or dementia." (PMID 26010883, 2015). "PTH's potential involvement with dementia may be explained in the following way: PTH has been shown to cross the blood-brain barrier." (PMID 19825157, 2009). "Based on our findings, we suggest that control of PTH levels may be important for protecting against age-induced dementia." (PMID 19825157, 2009). "On univariate analyses these included age, sex, CAD, dementia, ASA ≥ 3, smoking, eGFR, haemoglobin, 25(OH)D, PTH, leptin, adiponectin and resistin levels, but with different impact on specific outcomes by HF type." (PMID 22333003, 2012). "Main findings of non-surgical studies relating to PTH levels, parathyroid conditions, cognitive function and dementia." (PMID 26010883, 2015).
dementia (continued). "Some studies support a significant link between PTH levels and dementia whereas others do not." (PMID 26010883, 2015).
cyst (16 papers, 2009 to 2025). A sac-like closed membranous structure that may be empty or contain fluid or amorphous material. "Even though cystic parathyroid adenoma is a rare diagnosis, it should be considered in the differential diagnosis of neck masses and measurement of PTH in aspirated cyst fluid is highly recommended." (PMID 41383495, 2025). "A key diagnostic step is fine-needle aspiration (FNA), where elevated parathyroid hormone (PTH) in the cyst fluid can confirm its parathyroid origin, even if blood PTH levels are normal." (PMID 41209489, 2025). "Surgical excision is necessary to confirm a PC diagnosis via histological analysis of parathyroid tissue within the cyst wall and postoperative correction of PTH levels following cyst removal." (PMID 39295728, 2024). "The functioning nature of the cyst was also confirmed by the normalization of PTH after removal of the cystic parathyroid gland." (PMID 37568342, 2023). "Both types are characterized by highly elevated PTH levels in the cyst fluid, however, increased PTH serum levels were described only in secreting lesions." (PMID 37568342, 2023). "Two PTH-WO-positive patients with cystic parathyroid lesions were not operated, as they went into remission after aspiration of the cyst with PTH-WO." (PMID 37745742, 2023). "It is noted that intact-PTH concentration of the fluid in the cyst was very high (19,960,000 pg/mL)." (PMID 36544116, 2022). "Since we suspected ectopic PTH-producing cyst-like tumor in the upper superior mediastinum, we performed venous sampling of PTH." (PMID 36544116, 2022). "It is noted that intact-PTH concentration in the fluid in the cyst was very high (19,960,000 pg/mL)." (PMID 36544116, 2022). "In cases of non-functional cyst, US-guided fine-needle puncture with analysis of both thyroid hormones and PTH levels will determine the further management of the cyst." (PMID 29183364, 2017). "A left lower parathyroidectomy was successfully performed through a minimally invasive focused cervicotomy and intraoperative PTH levels went back to normal values within 15 minutes after cyst removal." (PMID 29183364, 2017). "US-guided puncture of the cyst revealed a PTH concentration of 4,347,000 pg/ml in the fluid, and normal thyroid hormone levels." (PMID 29183364, 2017). "First, the function of the cyst should be determined by the patient’s history and by measurement of plasma PTH and calcium levels (ionized calcium if available)." (PMID 29183364, 2017). "The diagnosis was made after aspiration of cyst fluid and detection of increased PTH concentration in this fluid." (PMID 25610671, 2014). "For a preoperative definitive diagnosis, we performed a parathyroid fine-needle aspiration (FNA) and PTH assay (PTH–FNA) of the liquid aspirated from the cyst." (PMID 25379182, 2014). "For preoperative definitive diagnosis, we carried out a parathyroid fine-needle aspiration (FNA) and PTH assay (PTH–FNA) of liquid aspirated from the cyst." (PMID 25379182, 2014). "A preoperative diagnosis of a parathyroid cyst is possible by FNA of the cyst fluid and PTH determination." (PMID 25379182, 2014). "Surgical resection is the preferred treatment for cystic parathyroid lesions and intraoperative cyst rupture should be avoided, as it may lead to misleading elevations in PTH levels." (PMID 41383495, 2025). "Parathyroid hormone (PTH) and thyroglobulin (Tg) levels were measured in the cyst fluid." (PMID 41209489, 2025). "Based upon these findings, we finally diagnosed her as ectopic PTH-producing cyst-like tumor." (PMID 36544116, 2022). "She underwent anterosuperior mediastinal ectopic PTH-producing cyst-like tumor resection." (PMID 36544116, 2022). "We finally diagnosed her as ectopic PTH-producing cyst-like tumor with venous sampling of PTH." (PMID 36544116, 2022). "The remaining 3 cysts were diagnosed because of elevated PTH levels of cyst aspiration." (PMID 29409478, 2018).
cyst (continued). "Current laboratory practice is to perform an iPTH assay, which may underestimate the PTH levels of cyst fluid." (PMID 29409478, 2018). "Symptoms of overt parathyroid crisis can lead to confusion and even coma and might be due to cyst rupture with discharge of large amounts of PTH into the blood stream." (PMID 29183364, 2017). "Second, PTH may be secreted into the lumen of the cyst instead of the bloodstream." (PMID 26610856, 2015). "The diagnosis may be confirmed with parathormone (PTH) assessment in cyst fluid." (PMID 25610671, 2014). "In our case, cyst fluid aspiration for PTH analysis was not performed; however, the markedly elevated serum PTH levels and postoperative histopathological findings confirmed the diagnosis." (PMID 41383495, 2025). "Although parathyroid hormone levels were not measured preoperatively, normal serum calcium levels suggested that the cyst was likely non-functional." (PMID 40008367, 2025). "Elevated parathyroid hormone levels in the cystic fluid confirm the diagnosis, but do not indicate that the cyst is functioning." (PMID 20512295, 2009). "An elevated PTH concentration proves the parathyroid origin, however, only the blood test differentiates whether the cyst is active or not." (PMID 37568342, 2023). "However, i‐PTH level measurement is not recommended for parathyroid cysts because PTH is rapidly degraded into the biologically inactive C‐terminal peptide in the cyst fluid." (PMID 32833315, 2021). "Non-functional parathyroid cyst may also present increased intracystic PTH concentrations, but not as high as in functional cyst." (PMID 29183364, 2017).
metabolic bone disorder (16 papers, 2008 to 2026). A group of disorders that affect the bones secondary to increased levels of minerals or deficient levels of minerals such as calcium, magnesium, phosphorus, and vitamin D. Representative examples are osteomalacia, osteoporosis, and Paget disease. "This condition can cause bone metabolic disorders, stimulatethe secretion of parathyroid hormone by the parathyroid gland, and inducemyocardial fibrosis." (PMID 39076321, 2024). "Metabolic bone disorders primarily result from abnormalities in calcium and phosphorus metabolism, imbalance in parathyroid hormone (PTH), and deficiency in vitamin D, an important mediator of calcium metabolism." (PMID 38166774, 2024). "Normal levels of PTH ranges between 12 and 70 pg/mL and excessive secretion of PTH causes a metabolic bone disorder known as HPT." (PMID 25692050, 2015). "ROD is a metabolic bone disorder characterized by abnormal bone remodeling, accompanied by a pattern of changes in serum calcium, phosphate, parathyroid hormone (PTH), vitamin D, and fibroblast growth factor 23 (FGF-23)." (PMID 37870853, 2023). "In this study, WD can cause damage to the hypothalamus–pituitary–peripheral target gland axis, a decreased parathyroid hormone, resulting in bone metabolism disorders, and thus elevated levels of AKP." (PMID 36684333, 2022). "This relatively low dependency of PTH on serum vitamin D and renal function has to be taken into account, particularly in the clinical setting of individual patients, when a metabolic bone disorder is suspected." (PMID 33995282, 2021). "Compared to No-PTX patients group, the PTX patients group had a greater percentage of hemodialysis (HD) patients, longer dialysis vintage, and a greater prevalence of more severe bone metabolism disorders such as higher ln (intact PTH) (iPTH)." (PMID 27307101, 2016). "Four genes are proposed as markers for cardiovascular as well as bone metabolism disorders, namely the PTH, the TNF, leptin (LEP), as well as IL-6." (PMID 18266955, 2008). "Additionally, a divergence between PTH elevation and a decline in bone turnover, which shown a special change of bone metabolism after IS and may suggest potential therapeutic implications of cold exercise in PTH and bone metabolic disorders." (PMID 34899374, 2021). "In general, CKD is associated with mineral and bone metabolism disorders arising due to either one or a combination of the following factors: abnormalities of phosphorus, Fibroblast Growth Factor-23 (FGF23), calcium, parathyroid hormone (PTH), and vitamin D metabolism." (PMID 32257685, 2020). "Parathyroid hormone and vitamin D are crucial regulators of Ca and PHOS and are widely used in diagnosing and treating bone metabolism disorders." (PMID 40463748, 2025).
Pruritus (16 papers, 2005 to 2025). Pruritus is an itch or a sensation that makes a person want to scratch. "Intact parathyroid hormone (iPTH) was also significantly associated with pruritus, with a 115 pg/mL mean difference between groups and independent predictive value in multivariate analysis (OR = 1.007; 95% CI: 1.003-1.010; p < 0.001)." (PMID 40666577, 2025). "The other findings of their study were contradicting with our results such as blood urea nitrogen >81 mg/dL with OR 1.4 and calcium >9.5 mg/dL with OR 1.4 were more associated, while PTH <200 pg/mL with OR 0.6 was less likely to be associated with pruritus." (PMID 34646616, 2021). "Another study reported a much higher prevalence of pruritus than our study (48% vs 37%) with significant associations including onset coincident with starting dialysis, the persistence of symptoms, elevated phosphate, parathyroid hormone (PTH), and blood urea nitrogen (BUN) level." (PMID 34646616, 2021). "The distribution score of pruritus was directly correlated with the age (Spearman's rho = 0.42, P = 0.02) and serum level of parathyroid hormone (PTH) (Spearman's rho = 0.42, P = 0.04)." (PMID 34367296, 2021). "In some studies, the increase of dialysis dose measured by Kt/V correlated with lesser intensity of pruritus, which means that filtration of certain metabolites (e.g., PTH, β2-microglobulin) could help reduce the intensity of pruritus." (PMID 40724504, 2025). "However, one study indicate that neither PTH, nor calcium and phosphate are associated with pruritus." (PMID 40630124, 2025). "Additionally, injecting PTH does not cause pruritus, suggesting that it has no primary role in activating itch fibers." (PMID 34437400, 2021). "Similarly, in our study, the increase in the PTH level was not correlated with the intensity of pruritus yet was interestingly associated with distribution of pruritus." (PMID 34367296, 2021). "In our study, although treatment group showed relatively higher phosphate and PTH, the degree of pruritus was milder, confirming that HSK21542 may has a powerful efficacy for pruritus." (PMID 40630124, 2025). "We also found that a weekly total Kt/V of less than 1.88, a longer duration of dialysis, a higher dietary protein intake, and higher blood levels of intact parathyroid hormone and high-sensitivity C-reactive protein were independent determinants of higher VAS scores of pruritus intensity." (PMID 30183756, 2018). "The levels of calcium, phosphorus, PTH, histamine, substance P, PAR-2, and tryptase were also measured as biochemical factors that might contribute to pruritus." (PMID 26495017, 2015). "Patients with UP showed significantly higher age, dialysis duration, hemoglobin, phosphorus, uric acid, intact PTH, hs-CRP, magnesium, and triglyceride levels compared to those without pruritus." (PMID 40666577, 2025).
metabolic acidosis (15 papers, 2005 to 2025). "Metabolic acidosis also negatively affects bone mineralization by increasing parathyroid hormone (PTH) production and suppressing collagen production by osteoblasts, resulting in calcium withdrawal from the bones and increased urinary excretion." (PMID 40739997, 2025). "Metabolic acidosis has been shown to stimulate PTH secretion; however, this only occurs when plasma ionized calcium levels are clamped." (PMID 35268016, 2022).